HMGB1 (high mobility group box 1)
Diseases named in the same sentence as HMGB1 in open-access papers (continued):
Sharing a sentence is not in itself a finding about the gene and the disease.
cancer (continued). "HMGB1 has attracted researchers since it was discovered in 1973, because it plays a critical role in various diseases and disorders, especially in inflammatory, immune responses, and hypoxia in cancer microenvironment." (PMID 26393575, 2015). "Further studies are required to confirm the involvement of these pathways in relevant biological systems, e.g., whether the redox status of HMGB1 induced by frankincense essential oil is involved in cancer cell-specific activity." (PMID 25006348, 2014). "Using ‘dead cancer-CM’, our results indicate that HMGB1 may be one component released by dying cells that can influence the response of other cancer cells to Dox." (PMID 25512109, 2014). "Interestingly, the CM derived from BCFs induced the production of HMGB1 in cancer cells in a time-dependent manner to a significantly greater degree than the CM from NTFs derived from adjacent non-involved breast tissue in the same patient." (PMID 25512109, 2014). "It has been recognized that HMGB1 has important roles in inflammation and cancer." (PMID 25118798, 2014). "We next tested the role of HMGB1 expression in regulation of cancer cell metastasis in an in vivo animal model by observing the liver metastatic ability of A549 transfectants of shControl and A549 shHMGB1 by tail veins-injection of the transfectants into the 4-week-old nude mice." (PMID 25277185, 2014). "HMGB1 released as DAMPs is widely demonstrated in necrotic cancer cells and only recently has been reported that apoptotic and autophagic cancer cells might release HMGB1 at some points in their execution phases." (PMID 25140900, 2014). "Accumulating evidence indicate that HMGB1 can function either inside or outside of a cell, and the extracellular HMGB1 plays an important role in inflammation that contributes to the development of cancer." (PMID 25051367, 2014). "Finally, it has been shown that host cells, in particular neutrophils and macrophages, are activated by cytokines as part of an innate immune response to cancer cells and actively secrete HMGB1." (PMID 25512109, 2014). "As a pro-survival protein, HMGB1 promotes cancer growth and development." (PMID 24996221, 2014). "HMGB1 may then be released from cancer cells during radiotherapy or chemotherapy and act upon surviving cancer cells to promote regrowth and metastasis." (PMID 25512109, 2014). "In contrast, some studies have reported active secretion of HMGB1 from certain types of cancer." (PMID 25512109, 2014). "HMGB1 had a strong staining in carcinoma tissues compared to normal tissues (p < 0.05)." (PMID 24837834, 2014). "HMGB1 may be involved in cancer progression and prognosis, including apoptosis, angiogenesis, the inflammatory microenvironment, mobility, invasion, metastasis and patient survival." (PMID 23426143, 2013). "The evidence for role of HMGB1 in cancer progression is now rapidly accumulating." (PMID 23766911, 2013). "Interestingly, HMGB1 is involved in cell proliferation, angiogenesis, and metastasis during cancer progression." (PMID 23766911, 2013). "Finally, activated innate immune cells and elicited adaptive anti-cancer immunity as well as inflammatory cytokines kill additional cancer cells and stromal cells, leading to release of DAMPs such as HMGB1." (PMID 24020520, 2013). "Previous studies have shown the oncogenic role of HMGB1 in cancer." (PMID 24098490, 2013). "HMGB1 is known to be consistently overexpressed in cancer cells compared to normal cell types." (PMID 23766911, 2013). "It is also to note that among RAGE ligands, HMGB1 appears to play an important role in cancer." (PMID 24710526, 2012). "When we compared the median value of HMGB1 between control subjects and cancer patients, we couldn't identify statistical significance between two groups, implying high variation of the values for HMGB1 in our population may affect the mean value." (PMID 22496788, 2012). "HMGB1 has been reported to be related to poor prognosis in cancer patients." (PMID 22496788, 2012).
cancer (continued). "Instead, cancer cells are known to possess cytoplasmic HMGB1 in its resting state." (PMID 22496788, 2012). "Another report suggested that extracellular HMGB1, secreted by necrotic cancer cells, might contribute to cancer cell survival, proliferation, and invasion." (PMID 22496788, 2012). "In addition to these reports, HMGB1 has been detected in the sera of patients with various cancers, including cervical, lung, gastric, and liver cancers." (PMID 22496788, 2012). "Interestingly, another proinflammatory mediator (high-mobility group box 1, HMGB1), which was also released under stress regulates autophagy and apoptosis in cancer cells." (PMID 22629429, 2012). "High mobility group box 1(HMGB1) overexpression has been reported in a variety of human cancers." (PMID 22747650, 2012). "In cancer, the roles of HMGB1 have been suggested on the basis of its roles in immune cells." (PMID 22496788, 2012). "Interestingly, HMGB1 itself is critical for the survival of cancer cells since knockdown of HMGB1 results in a caspase-3-dependent apoptosis." (PMID 24212771, 2011). "In addition, the HMGB1 protein triggers autophagy or apoptosis in cancer cells, depending on its redox status." (PMID 21917150, 2011). "However, further basic and clinical studies are warranted to confirm the roles played by HMGB1 in clinical cancer medicine." (PMID 20579387, 2010). "Multivariate analysis showed that the expected cancer-free survival time was 20.4375 ± 7.28648 m for tumors with HMGB1 overexpression (95% CI = 17.8104 - 23.0646), 15.5870 ± 8.23158 m for tumors with HMGB1 no-and low-level expression (95% CI = 13.1425 - 18.0314)." (PMID 20579387, 2010). "Recently, the unique ability of doxorubicin, daunorubicin and mitoxantrone to make cancer cells immunogenic was shown to be through calreticulin re-localization to the cell surface and the selective induction and release of High-mobility group box 1 (HMGB1) protein from dying cancer cells." (PMID 20626886, 2010). "The controversy indicates that HMGB1 may affect the treatment response of cancers, and HMGB1 may affect the prognosis through complicated pathways." (PMID 20579387, 2010). "HMGB1 levels are related with the clinicopathologic characteristics in many cancers." (PMID 20579387, 2010). "Which signaling pathways are fundamental for describing HMGB1 signal transduction, and what mechanisms are responsible to explain recent results linking overexpression of HMGB1 with decrease of apoptosis (and increased cancer cell survival)?" (PMID 21106117, 2010). "Therefore, individual studies of HMGB1 levels in each type of cancer are needed to obtain a more accurate understanding of HMGB1-related mechanisms in cancer development and progression." (PMID 19476625, 2009). "Our findings showed that ICM treatment inhibited the phosphorylation of constitutively activated STAT3, suggesting that targeting the nucleo-cytoplasmic translocation of HMGB1 may offer a potential therapeutic strategy against cancers with constitutive STAT3 activation." (PMID 40389855, 2025). "IL-1β and HMGB1 may contribute to cancer growth and progression." (PMID 40422244, 2025). "Based on these data, a potential mechanism through which HMGB1 promotes anti-PD-1/PD-L1 therapy-mediated anticancer immunity might be explained as follows; in general, cancer immunity cycle, which involves several important steps, is proposed to explain the mechanism of action of ICIs." (PMID 39853458, 2025). "Thus, modulating HMGB1 may provide a potential combined strategy for cancer radiotherapy and immunotherapy." (PMID 41296391, 2025). "The presence of HMGB1 further enhances the apoptotic effect at higher concentrations, suggesting that Paliperidone could be a potent inducer of apoptosis in cancer cells, providing a strong basis for its potential therapeutic application in cancer treatment." (PMID 39940823, 2025).
cancer (continued). "Additionally, a clinical study involving 202 cancer patients treated with an OAd identified low baseline serum levels of high mobility group box 1 protein (HMGB1) as an independent positive prognostic and predictive factor for oncolytic immunotherapy in individuals with advanced cancer." (PMID 40698086, 2025). "The correlation between DAMPs and clinical symptoms of cancer has been reported by several studies as either a positive or a negative correlation, for example, high HMGB1 levels proportionally associated with poor overall survival in patients with advanced hepatocarcinoma treatment." (PMID 39768997, 2024). "Hence, HMGB1 emerges as a key player in cancer-induced myocardial damage." (PMID 38731953, 2024). "Notably, CRC elevates HMGB1 secretion levels, correlating with cancer progression severity." (PMID 38731953, 2024). "Thus, the novel approach by which HMGB1 drives the progression of GC may offer fresh perspectives on enhancing the effectiveness of cancer immunotherapy." (PMID 39061213, 2024). "Thus, the exact mechanisms of HMGB1 in cancer still need more research." (PMID 38576043, 2024). "The study suggested that New FP therapy, a locoregional therapy with high local control potential, might have promoted step 1, as indicated by increased MHC-I-positive cells and serum HMGB1 and accelerated rotation of the cancer-immunity cycle, resulting in long PFS and OS." (PMID 39131724, 2024). "We hypothesize that blocking the cross-talk between RAGE and HMGB1 may inhibit cancer progression." (PMID 39335163, 2024). "Furthermore, HMGB1 acts as an autocrine/paracrine growth factor in many cancers, enhancing malignant phenotypes and disease recurrence, and the suppression of HMGB1 by CT is thought to play a role in maintaining antitumor effects during cancer chemotherapy." (PMID 39796128, 2024). "Thus, HMGB1 emerges as a critical mediator of myocardial damage in cancer." (PMID 38731953, 2024). "Taken together, our results support a model in which HMGB1 binds to multiple RNA species in human cancer cells, which could at least partially contribute to HMGB1-modulated rRNA modification, protein synthesis function of ribosomes, and differential gene expression including rRNA genes." (PMID 38580917, 2024). "Moreover, it was reported that the HMGB1 released by cancer cells undergoing ferroptosis could increase the tumor necrosis factor α (TNFα) of macrophages." (PMID 36926345, 2023). "High-mobility group box 1 (HMGB1) is a highly conserved DNA-binding protein ubiquitous in mammalian cells, involved in maintaining nucleosome structure and regulating the transcription of various genes, and has been found abnormally expressed in many human cancers." (PMID 36709284, 2023). "While assessing HMGB1 expression in CaP, there was a striking pattern of moderate/strong nuclear and cytoplasmic HMGB1 expression apparent in 77% of the CaP at the invasive cancer margin, the transitional space where cancerous cells invade normal or adenomatous epithelium." (PMID 36980751, 2023). "However, the delivery method of HMGB1 from TAMs to cancer cells is still unknown, and the downstream regulatory mechanism needs to be further explored." (PMID 36709284, 2023). "In our large, well characterised cohort, we have identified an HMGB1 expression profile switch with dynamic subcellular localisation between normal and T1 malignancy, and a striking HMGB1 expression signature at the leading invasive edge in the majority of polyp cancer lesions." (PMID 36980751, 2023).
cancer (continued). "The levels of HMGB1 were determined in the cancer cells after co-culture with macrophages to further investigate whether the macrophage-derived HMGB1 was taken up by cancer cells to promote cancer progression." (PMID 36709284, 2023). "High mobility group box 1 (HMGB-1) was recently found to function as a damage-associated molecular pattern (DAMP) when released passively from either dead, dying/injured cells or secreted by immune/cancer cells in response to endogenous and/or exogenous stimuli, such as hypoxia, endotoxin etc.." (PMID 37649540, 2023). "Ferroptosis is a pathway of immunogenic cell death characterized by iron-dependent lipid peroxidation and HMGB1 release that may have particular therapeutic importance in oncology, as cancer cells of numerous histological types are known to be uniquely susceptible to ferroptosis." (PMID 36756111, 2023). "Moreover, miRNAs can affect HMGB1 gene expression, modulating cancer progression." (PMID 35269471, 2022). "Thus, we further investigated the post‐translation features of HMGB1 in 33 cancers." (PMID 35765707, 2022). "Notably, besides the release of several DAMPs from dying cancer cells (e.g., ATP, HMGB1, CRT, ERp57, HSP90 and vasostatin) the suppression of CD47 (the “don’t eat me” signal) and up-regulation of inflammatory chemokines (CXCL1–3, 10, 12 and 13) have also been observed." (PMID 35562364, 2022). "In addition to the nuclear and extracellular roles of HMGB1, cytoplasmic HMGB1 could bind many proteins involved in autophagy, cancer evolution and unconventional secretory pathways." (PMID 35720285, 2022). "Furthermore, this study studied the genetic disorders of HMGB1 in cancer." (PMID 35765707, 2022). "However, HMGB1 still plays a role in promoting cancer development." (PMID 35359956, 2022). "Additionally, an elevated HMGB1 expression level has been reported in cancer cells." (PMID 35336794, 2022). "Thus, inhibiting HMGB1 stops its loop of action, affecting both cancer cells and neutrophils." (PMID 36555469, 2022). "Therefore, the combination of HMGB1 and ICPs might closely impact the immunotherapy efficacy in diverse cancers." (PMID 36230798, 2022). "Additionally, we showed that cancer-derived HMGB1 conditioned B cells could maintain a proangiogenic TME in ESCC." (PMID 34617194, 2022). "Trafficking and localization of HMGB1 across cellular compartments could be regulated by its posttranslational modifications, which fine‐tune its functions in metabolic diseases, inflammation and cancers." (PMID 35706377, 2022). "Conversely, the release of HMGB1 may result in the dedifferentiation of cancer cells." (PMID 35637945, 2022). "The complex role of HMGB1 in cancer cells may depend on the pattern in which HMGB1 is induced." (PMID 35637945, 2022). "Finally, we show that HMGB1-ΔC retains the capacity of the full-length protein to perturb the metabolism of cancer cells even if the capacity of the cells to circumvent oxidative phosphorylation inhibition might determine their cellular outcome." (PMID 35887213, 2022). "Thus, it is expected that papaverine-mimetic 3-styrylchromone derivatives, which possess both potent anti-inflammatory and anti-cancer activities targeting the HMGB1-RAGE axis, may become valuable leads for developing a new type of anti-cancer pharmaceutical." (PMID 35408786, 2022). "In addition, although there was a study showing that HMGB1 release was not different between X-ray and carbon-ion irradiation with iso-survival doses, another study found that HMGB1 release after carbon-ion irradiation increased along with linear energy transfer (LET) in cancer cells." (PMID 35008367, 2021). "Depending on the type of cancer, investigated subgroups, geographical distribution, sample size and detection method, the authors reported hazard ratios for overall survival between 1.54 and 2.93, indicating longer overall survival in patients with low concentrations of HMGB1." (PMID 33672622, 2021).
cancer (continued). "High-mobility group box 1 protein (HMGB1), which performs dual functions as a highly conserved chromosomal protein that enhances transcription and is a crucial cytokine that mediates the response to infection, injury and inflammation, has been reported to play a paradoxical role in cancer." (PMID 34257571, 2021). "However, recent discoveries that HMGB1 released from neurons mediates inflammation via the TLR4 receptor system, and that cancer cells express fully oxidized HMGB1 as an immunosuppressive mechanism, offer new paths to targeting HMGB1 for inflammation, pain, and cancer." (PMID 34943830, 2021). "As HMGB1 rs1045411 polymorphism is closely correlated with altered binding of miR-505-5P in the 3'-UTR of mRNA transcripts, HMGB1 gene polymorphisms could emerge as a crucial player in cancer development through a post-transcriptional mechanism." (PMID 33628090, 2021). "Therefore, CML modification of HMGB1 enhanced the cancer-promoting effect of HMGB1." (PMID 34068442, 2021). "Furthermore, HMGB1/RAGE axis was seen to be crucial during the development of the inflammation, and activation of HMGB1/RAGE axis could also promote the development of various sorts of cancer by inducing inflammation." (PMID 34369271, 2021). "Glycyrrhizin, HMGB1 inhibitor, may be a potent drug in cancer cachexia." (PMID 34867338, 2021). "Importantly, HMGB1 is a crucial regulator in cancer biology." (PMID 33926347, 2021). "Initially, the results from the Oncomine database showed that HMGB1/2/3 were significantly highly expressed in a total of 22, 22, and 51 datasets, whereas they were lowly expressed in two, three, and one datasets of various cancers, respectively, compared with paired normal controls." (PMID 34777483, 2021). "Thus, understanding the molecular bases of HMGB1 might be important for exploring its precise role in cancer." (PMID 33628090, 2021). "In addition, it is possible nuclear HMGB1 could serve as a prognostic biomarker, given its elevated levels in cancer cells that reflect the proliferative state of the cell." (PMID 34680084, 2021). "Importantly, released HMGB1 acts as a so-called “danger signal” and could impact on the ability of cancer cells to escape host immune surveillance." (PMID 34234778, 2021). "In addition to apoptosis and necrosis, we examined glucose consumption, which is closely related to nutrient deprivation in cancer, increasing at early stages and slowing down when cells undergo apoptosis 14, and high‐mobility group box 1 (HMGB1) protein release, which is a feature of necrosis." (PMID 32647502, 2020). "It is reported that the high level of HMGB1 promotes the migration, invasion, and autophagy of cancer cells, which was inhibited by GL, indicating that GL may exert an antitumor effect and possibly improve the efficacy of radiotherapy in the treatment of the tumors." (PMID 32595744, 2020). "Therefore, upregulation of these miRNAs with HMGB1-RAGE helps cancer progression." (PMID 32443845, 2020). "Interestingly, irradiated osteocytes can promote osteoclastogenesis through the release of HMGB1 (high mobility group box 1) followed by an elevation of the RANK-L/OPG (osteoprotegerin) levels, indicating a key role for osteocytes in IR-induced bone loss during cancer therapy." (PMID 32887421, 2020). "The function and molecular mechanisms of HMGB1 remain unclear in cancer." (PMID 33122771, 2020). "The ROS generation and related activation of p38MAPK and NF-κB signals are considered responsible for ATP-induced HMGB1 release from macrophages, being identical to the molecular mechanisms for the release of HMGB1 from macrophages in response to paclitaxel, an anti-cancer agent." (PMID 32707767, 2020). "In cancer cells, it has been suggested that HMGB1 may be involved in autophagy." (PMID 32155899, 2020).